ENSG00000275856
Gene: Miscellaneous RNA gene on chromosome 6 (30,058,115 to 30,058,190, forward strand). Ensembl gene ENSG00000275856.
Homologues: Orthologues: mouse Gm55934 (79% identical).